BNIPL (BCL2 interacting protein like)
Description:
May be a bridge molecule between BCL2 and ARHGAP1/CDC42 in promoting cell death.
Synonyms: BNIPl-1; BNIPL-2; PP753; BNIP-S; BNIP-Salpha; BNIP-Sbeta; BNIPL1; BNIPL2; BNIPS
Tractability: No criterion of Open Targets' tractability assessment is met for any kind of drug.
Gene: Protein-coding gene on chromosome 1 (151,036,321 to 151,047,720, forward strand). Ensembl gene ENSG00000163141.
Subcellular location (Human Protein Atlas): Cytosol
Gene Ontology:
Molecular function: identical protein binding; protein binding
Biological process: apoptotic process; negative regulation of cell population proliferation; regulation of growth rate
Cellular component: cytosol; nucleus; cytoplasm
Genetic constraint (gnomAD): Loss-of-function variants: 32 observed, 47.2 expected, observed/expected ratio (o/e) 0.68, 90% interval 0.51 to 0.91. The upper end of that interval is the gene's LOEUF score, 0.91, which puts it in group 3 of 6, group 1 being the genes least tolerant of losing a copy. Missense variants: 404 observed, 456.04 expected, observed/expected ratio (o/e) 0.89, 90% interval 0.82 to 0.96. Synonymous variants: 145 observed, 167.82 expected, observed/expected ratio (o/e) 0.86, 90% interval 0.75 to 0.99.
Homologues: Orthologues: chimpanzee BNIPL (99% identical), macaque BNIPL (92% identical), pig BNIPL (87% identical), rabbit BNIPL (87% identical), dog BNIPL (84% identical), rat Bnipl (84% identical), mouse Bnipl (83% identical), guinea pig BNIPL (78% identical), tropical clawed frog bnipl (46% identical), zebrafish bnipl (42% identical), Drosophila melanogaster CG11593 (32% identical). Paralogues in human: BNIP2 (42% identical), PRUNE2 (38% identical), ATCAY (37% identical).
Diseases named in the same sentence as BNIPL in open-access papers:
BNIPL is named in the same sentence as 9 diseases in open-access papers, as found by Europe PMC text mining. Sharing a sentence is not in itself a finding about the gene and the disease. The quoted sentences say what the papers report.
breast carcinoma (1 paper, 2022). "Survival analysis also indicated the overexpression of TXNL1 and BNIPL in breast cancer is significantly associated with poor overall survival." (PMID 36230901, 2022). "Our validation analysis confirmed that the gain of 5-hmC in TXNL1, BNIPL, CNIH3 and loss of 5-hmC in CHODL, ZBTB16, SP8, and HIC2 in breast cancer samples." (PMID 36230901, 2022). "Novel 5-hmC candidates such as TXNL1, CNIH3, BNIPL, and CHODL were found to be promising diagnostic and therapeutic markers for breast cancer." (PMID 36230901, 2022).
cervical cancer (1 paper, 2021). A primary or metastatic malignant neoplasm involving the cervix. "Approximately one third (7 of 19; SPRR2G, RAET1G, FOXA2, BNIPL, LOR, LCE2B, and LCE1B) had expression that was highest among the NED/Stage1/Stage2 cluster, lower in the premalignant cluster, and even lower in Stage 3 cervical cancer tissue." (PMID 34944802, 2021).
colorectal cancer (1 paper, 2024). A primary or metastatic malignant neoplasm that affects the colon or rectum. "In addition, overexpression of CD44 restores the cell proliferation suppressed by BNIPL‐2 and BNIPL-2, which can promote migration, invasion, and metastasis of colorectal cancer cells via CD44." (PMID 38302910, 2024).
hepatocellular carcinoma (1 paper, 2024). A malignant tumor that arises from hepatocytes. "Overexpression of BNIPL-2 can significantly inhibit tumor growth by regulating molecules related to cell proliferation and apoptosis of hepatocellular carcinoma cells." (PMID 38302910, 2024). "Additionally, BNIPL-2 can interact with Bcl-2 and Cdc42GAP to regulate cell apoptosis in hepatocellular carcinoma." (PMID 38302910, 2024).
lung carcinoma (1 paper, 2022). "Among the downregulated and hypermethylated genes associated with both RMST and DIRC3 (including BNIPL, HORMAD2, and NPHP3), HORMAD2 is the only gene related to lung cancer." (PMID 35356464, 2022).
cancer (3 papers, 2018 to 2024). A tumor composed of atypical neoplastic, often pleomorphic cells that invade other tissues. "Several studies investigate the effect of BNIPL-related molecules on cancer cell function: growth, migration, and invasion by regulating expression levels." (PMID 38302910, 2024). "We found that five genes were related to cancer, including BNIPL, ERBB3 and PRKG1, which were also been detected by degree or eigenvector measures." (PMID 29301256, 2018). "There are few reports focusing on the role of BNIPL in cancers." (PMID 38302910, 2024). "This inspires us that BNIPL may play an important role in cancer cells in two pathways: regulating DNA breakage and vesicle formation in apoptotic cells." (PMID 38302910, 2024).
BNIPL also shares sentences with these, for which no sentence is quoted: laryngeal carcinoma (1 paper); lung adenocarcinoma (1); nephronophthisis (1).